SMIM47 (small integral membrane protein 47)
Tractability: Antibody: UniProt predicts a signal peptide or a membrane-spanning region.
Gene: Protein-coding gene on chromosome 19 (50,776,141 to 50,793,142, reverse strand). Ensembl gene ENSG00000261341.
Subcellular location: Membrane
Gene Ontology:
Cellular component: membrane
Homologues: Orthologues: mouse Gm15517 (89% identical), rat Smim47 (86% identical).